CEBPD (CCAAT enhancer binding protein delta)
Diseases named in the same sentence as CEBPD in open-access papers (continued):
Sharing a sentence is not in itself a finding about the gene and the disease.
tumor (99 papers, 2007 to 2026). "Within that CIN region, amplification of CCAAT/enhancer‐binding protein delta (CEBPD) was linked to an adverse prognosis due to rapid tumour proliferation and metastasis." (PMID 34954904, 2021). "Past studies have implicated ATF5, CEBPB and CEBPD in the regulation of cancer cell responsiveness to the microtubule-targeting drug Taxol (paclitaxel), which is used to treat breast and other tumor types." (PMID 34065488, 2021). "RBPs like TTP, HuR, AUF1, CUGBP1 and CEBPδ can directly or indirectly control turnover of mRNAs encoding tumor pathogenesis-related factors." (PMID 31023373, 2019). "CEBPD is thought to function as a tumor suppressor in cancer cells because the loss of CEBPD promotes tumor progression." (PMID 26124179, 2015). "However, in certain malignancies, aberrant overexpression of CEBPD has been linked to tumor progression and metastasis, potentially enhancing tumor cell survival and dissemination." (PMID 40895068, 2025). "Importantly, PTX3 levels in the blood of experimental mice bearing allograft E0771‐Luc2 tumours were correlated with the expression of CEBPD and were positively associated with growth and metastasis." (PMID 35090088, 2022). "Bortezomib was found to activate CEBPD (CCAAT/enhancer binding protein delta), a transcription factor associated with cellular differentiation, motility and cell death, thereby functioning as a tumor suppressor in various cancers by promoting apoptosis and cell cycle arrest." (PMID 34358067, 2021). "Furthermore, knocking down CEBPδ may help to maintain the anti-metastatic ability because it will prevent tumor-associated exhaustion in NK cells." (PMID 36890150, 2023). "The transcription factor CCAAT enhancer binding protein delta (C/EBPδ) is implicated in having a regulatory role in diverse biological functions such as acute-phase response (reaction to inflammation), growth arrest, apoptosis, differentiation, stem cell self-renewal, and tumor suppression." (PMID 30781689, 2019). "Dpep is a cell-penetrating peptide that targets transcription factors ATF5, CEBPB and CEBPD to selectively suppress growth and survival of diverse tumor cell types in vitro and in vivo." (PMID 42121927, 2026). "Accumulating evidence has shown that macrophage CEBPD plays crucial roles in tumor escape, drug resistance, metastasis, and invasion." (PMID 40990024, 2025). "It has been demonstrated that the expression of CEBPD can be activated under conditions of ER stress in tumor cells." (PMID 41408309, 2025). "Collectively, these findings strongly suggested that the knockdown of CEBPD had the effect of suppressing tumor development by impeding cell activity, proliferation, migration, and invasion." (PMID 40114930, 2025). "Through these experiments, it was observed that the knockout of CEBPD inhibited the activity, migration, and proliferation of TCs, thereby suppressing tumor growth." (PMID 40114930, 2025). "In IHC analysis, increased expression of CEBPD also be found in Resistance tumor, as well as the results in two external cohort." (PMID 40303328, 2025). "To exclude possible paracrine effects, we first tested the effect of C/EBPδ on (neighboring) tumor cells in vitro using a doxycycline-inducible CEBPD overexpression system." (PMID 39273396, 2024). "The transcriptional factor, CEBPD, plays a crucial role in tumor development, metastasis, and resistance to therapies, as well as being distinguished as a driver of maintaining cancer stemness." (PMID 38892210, 2024). "Previous studies have indicated that its role in inflammation and tumours is bidirectional; however, in most cases, CEBPD promotes inflammation." (PMID 39730319, 2024). "CCAAT/enhancer‐binding protein delta (CEBPD) is expressed at low levels in most normal tissues, upregulated by inflammatory factors, hormones and the tumour microenvironment." (PMID 39730319, 2024).
tumor (continued). "The number of homing tumor cells in tumor-bearing lungs decreased significantly after the pre-infusion of CEBPδ-siRNA-treated liver CD45+ cells derived from tumor-bearing mice compared to control siRNA-treated cells." (PMID 36890150, 2023). "CEBPD has been demonstrated to promote growth, metastasis, and drug resistance in multiple tumor types and can serve as a potential target for cancer treatment." (PMID 37017469, 2023). "Fluorescent-labeled tumor cells were cocultured with control siRNA- or CEBPδ-siRNA-treated B220+CD11c+NK1.1+ NK cells to calculate the number of dead tumor cells." (PMID 36890150, 2023). "Aberrant CCAAT/enhancer-binding protein delta (CEBPD), a transcription factor, displays an oncogene or tumor suppressor depending on tumor type and microenvironments." (PMID 36776299, 2023). "Since following the increase of CEBPδ expression in the late pre-metastatic phase, the Vtn expression level of the anti-tumor NK cell was decreased, it should be the first method to knockdown CEBPδ to regain the Vtn expression." (PMID 36890150, 2023). "Dpep is a cell-penetrating peptide targeting transcription factors ATF5, CEBPB, and CEBPD, and that selectively promotes the apoptotic death of multiple tumor cell types in vitro and in vivo." (PMID 38001578, 2023). "We highlight one such strategy, namely, the design of cell-penetrating dominant-negative decoy peptides that exploit the leucine zipper properties of ATF5 and/or CEBPB and CEBPD, and that selectively suppress the growth and survival of tumor cells." (PMID 36831248, 2023). "Semi-quantitative analysis revealed that CEBPD staining scores increased along with tumor grade and is significantly higher in GBM than in normal brain and LGGs." (PMID 37059730, 2023). "To investigate the effect of the liver environment on Vtn and Tsp expression, we cultured CEBPδ-siRNA-treated tumor-bearing liver CD45+ cells in a liver-conditioned medium (LiCM)." (PMID 36890150, 2023). "As reviewed here, perturbation of ATF5/CEBPB/CEBPD affects a variety of properties of brain and other tumor cells such as their survival, growth, migration, mesenchymal transition, and response to therapeutics." (PMID 36831248, 2023). "Mice tumor models revealed the effectiveness of Axitinib and Entinostat, two small molecule inhibitors targeting CEBPD and FOSL1 against tumors." (PMID 37441593, 2023). "We first screened NK cell transcription factors to determine that CEBPδ is a key transcription factor and demonstrated that knockdown of CEBPδ made NK cells into more anti-tumor character, implying that blocking CEBPδ prevents NK cell exhaustion." (PMID 36890150, 2023). "After treating tumor-bearing liver CD45+ cells with CEBPδ-siRNA, we pre-injected these cells intravenously into tumor-bearing mice, followed by injection of fluorescent-labeled tumor cells (experimental model)." (PMID 36890150, 2023). "Compared to the knockdown control, xenografts bearing CEBPD knockdown exhibited significantly inhibited tumor growth and elevated TUNEL staining." (PMID 36035213, 2022). "Our previous studies showed that CEBPD functions as a tumor suppressor by inducing cell growth arrest and apoptosis in some cancers." (PMID 36035213, 2022). "CEBPD has many tumor suppressor-like properties and downregulated in several types of cancer, and its expression in tumors is associated with a favorable prognosis." (PMID 36510567, 2022). "A copious amount of literature links basic leucine zipper transcription factors, ATF5, CEBPB and CEBPD, to tumor formation, growth, metastasis and treatment resistance in a variety of cancers." (PMID 34065488, 2021). "IL6 and IL8 have been identified as direct CEBPB and CEBPD targets, and there is evidence that cancer-cell-derived IL-6 and IL-8 promote tumor growth and metastasis and therapeutic resistance." (PMID 34065488, 2021).
tumor (continued). "The in vivo effects of CEBPD overexpression in a high‐glucose environment on tumour growth were investigated in xenografted induced diabetic severe combined immunodeficiency/beige mice." (PMID 34954904, 2021). "Although no single mechanism controls the biological functions of cancer, we can elucidate the kinds of cancer in which CEBPD activation plays a tumor suppressive or oncogenic role." (PMID 33436575, 2021). "A higher level of CEBPD transcript was observed in the UCs compared to their non‐tumour counterparts." (PMID 34954904, 2021). "Stromal-cell-derived factor 4 (SDF4) is responsive to anticancer drugs via CEBPD activation in CAFs and contributes to create a permissive environment for tumor cell angiogenesis and promotion of distant metastasis." (PMID 33953165, 2021). "Taken together, these results indicated that high levels of serum leptin and pSTAT3/CEBPD/MCL1 axis activation were significantly associated with advanced clinical stages and tumor grades." (PMID 34156978, 2021). "To this end, we first looked at the site of the tumor and examined two publicly available microdissected mRNA datasets to investigate the expression of CEBPD mRNA in the tumor and tumor stroma." (PMID 34439745, 2021). "Inactivation of CEBPD has been suggested to benefit several types of cancer development, implying that it has a tumor-suppressive role." (PMID 34156978, 2021). "Moving away from the tumor into other tissues of the body, along with potential metastatic sites, we next assessed CEBPD mRNA expression in healthy tissue using the Genotype-Tissue Expression (GTEx) Project dataset." (PMID 34439745, 2021). "In keeping with previous results, the pSTAT3/CEBPD/MCL1 axis was upregulated in the HFD-fed tumor xenografts." (PMID 34156978, 2021). "We found that knockdown of CEBPD exhibited more CDDP-induced reduction of tumor growth and enhancement of cell apoptosis." (PMID 32661323, 2020). "The overexpression of CEBPD in these cancers can induce cancer cell apoptosis and inhibit cell growth, thus implying CEBPD’s role as a tumor suppressor." (PMID 31300060, 2019). "CEBPD is thought to be a potent tumor suppressor, as its overexpression can result in the death of cancer cells." (PMID 28099155, 2017). "Transcription factor CCAAT/enhancer-binding protein delta (CEBPD) has been suggested to serve as a tumor suppressor and is responsive to multiple anticancer drugs in HCC." (PMID 28099155, 2017). "CEBPB shares functional interactions with CXCL10/IP-10, and both CEBPB and CEBPD are known to be tumor suppressors." (PMID 27764787, 2016). "Though it was reported that CEBPD was induced by IFN-γ in certain cancers, CEBPD functions both as a tumor suppressor and a tumor promoter." (PMID 27172898, 2016). "CEBPD was initially designated as a tumor suppressor based on its physiological functions, including mediating growth arrest and promoting cell death." (PMID 26307680, 2015). "We next demonstrated that PTX3, a gene that is directly regulated by CEBPD, can fully support the protumor role of CEBPD in the tumor microenvironment." (PMID 26124179, 2015). "We found that activation of CEBPD in the tumor microenvironment contributed to the metastasis, invasion, acquired chemoresistance and stemness of cancer cells." (PMID 26124179, 2015). "The current study further supports our previous study showing CEBPD serves a protumor role in tumor microenvironment." (PMID 26124179, 2015). "Recently, a more detailed involvement of CEBPD in some of these inflammation-related diseases, and even in the tumor microenvironment, has been elucidated." (PMID 25591788, 2015). "We also confirmed positive associations between CEBPD amplification and overexpression and MMP2 expression in UC tumor samples." (PMID 26307680, 2015). "This study successfully revealed a new insight of CEBPD in the communication between cancer cells and the tumor microenvironment, especially in macrophages." (PMID 25591788, 2015).
tumor (continued). "CEBPD expression enhances tumor invasiveness by directly binding to the MMP2 promoter, resulting in transcriptional upregulation." (PMID 26307680, 2015). "In early-stage MF, we observed gene expression differences in cells of both the stroma and the immune system, with keratinocytes exhibiting increased interferon response and proliferation (STAT1, ICAM1, HLA-DRA, GJB2), while fibroblasts displayed tumour-associated programs (CXCL2, TNFAIP6, CEBPD)." (PMID 41888970, 2026). "The major aim of this work was to determine whether Dpep, a cell-penetrating peptide that targets the leucine zipper transcription factors ATF5, CEBPB, and CEBPD, could effectively sensitize tumor cells to the cytotoxic actions of NK-92MI cells." (PMID 40358191, 2025). "Additionally, a crucial transcription factor, CEBPD, was identified, which demonstrated a pronounced propensity towards tumors and harbored potential tumor-advancing characteristics." (PMID 40114930, 2025). "Similarly, the CD8+ T cells were sorted from the harvested xenograft tumor tissues, in which the cell exhaustion was decreased by sh-CEBPD but promoted by oe-VAMP3." (PMID 38627816, 2024). "We then examined whether liver B220+CD11c+NK1.1+ NK cells from a tumor-bearing mouse could regain their binding ability to fibrinogen when the CEBPδ was knocked down." (PMID 36890150, 2023). "CEBPD is a tumor suppressor and an important regulator of immune and inflammatory response." (PMID 37876943, 2023). "CEBPδ is a versatile modulator of gene transcription; its physiological functions vary with cell type and cellular context, but the mechanism of environment-specific regulation is unclear CEBPδ also reduced tumor incidence but promoted tumor metastasis in a mouse model." (PMID 36890150, 2023). "However, Tsp was downregulated in the presence of tumor-bearing LiCM following CEBPδ-siRNA administration, despite Vtn being upregulated under the same conditions." (PMID 36890150, 2023). "CEBPδ has a multifaceted role in tumor progression, acting as both a suppressor and a promoter." (PMID 36890150, 2023). "An in vivo xenograft study also confirmed the decreased tumor growth by CEBPD inhibition." (PMID 36035213, 2022). "In our published research, we showed that the regulation of CEBPD (CCAAT/enhancer-binding protein delta) on tumor growth is partially through the transcriptional suppression of hsa-miR-429 to promote glycolysis-related HK2 expression in UTUC- and UBUC-derived cell lines (BFTC909, TCCSUP)." (PMID 35203290, 2022). "Yet, we again found that CEBPD mRNA was widely expressed in the tumor stroma." (PMID 34439745, 2021). "ATF5, CEBPB and CEBPD are reported to promote tumor cell migration and metastasis." (PMID 34065488, 2021). "Consistently, UC specimens also represented higher CEBPD protein levels than non‐tumour urothelium." (PMID 34954904, 2021). "Moreover, in the tumor microenvironment, CEBPD plays a protumor role through inhibition of phagocytosis and enhancement of immunosuppression, stemness, metastasis, and invasion following certain stimuli, such as proinflammatory factors or anticancer drugs." (PMID 33953165, 2021). "Interestingly, CEBPD also plays a pro-tumorigenic role by promoting genome instability and anticancer drug resistance, indicating that CEBPD serves as a tumor suppressor or tumor promoter depending on the cancer cell context." (PMID 33953165, 2021). "As a tumor suppressor, CEBPD is inactivated in multiple cancer types, including leukemia." (PMID 34358067, 2021). "In addition to acting as a tumor suppressor, several recent reports have suggested that CEBPD plays an oncogenic role in certain conditions." (PMID 34156978, 2021). "CEBPD is a tumor suppressor, which identifies it as a bad candidate for repression." (PMID 32872640, 2020). "Additionally, PUM2 overexpression combined with knockdown of both UBE2I and CEBPD resulted in the smallest tumor volume among all the groups." (PMID 32997416, 2020).
tumor (continued). "CEBPD is involved in the regulation of apoptosis and cell proliferation and there is evidence that it might acts as tumour suppressor." (PMID 31999706, 2020). "Interestingly, however, CEBPD expression was decreased in tumor tissue as compared to the control tissue in both the GSE62452 and GSE16515 dataset." (PMID 32906832, 2020). "CEBPD plays a functional role in tumor formation and progression." (PMID 31300060, 2019). "Additionally, lung tumor metastasis was significantly lower when tumor cells were injected into a CEBPD-null mouse compared to a control." (PMID 30558204, 2018). "Previously, we suggested that PGE2-activated CEBPD may play a protumor role in the tumor microenvironment." (PMID 26124179, 2015). "Based on our current findings, we suggest CEBPD amplification/overexpression in tumor samples can be a surrogate biomarker to positively select patients that might benefit from MMP2 targeted therapy." (PMID 26307680, 2015). "Actually, the decreased lung metastasis may also implied that the existence of CEBPD in stromal cells, such as fibroblasts or macrophages, in tumor microenvironment might contribute to invasion/metastasis." (PMID 25591788, 2015). "Our study also indicates that the dissection of CEBPD biology in the tumor microenvironment could suggest targets for developing anticancer reagents, such as the RI37 peptides demonstrated here, that may be used for cancer therapy in the future (Figure." (PMID 26124179, 2015). "Interestingly, the tumour growth advantage conferred by CEBPD overexpression was even more exacerbated in mice with high‐fat‐diet‐induced DM than in those with mock cell‐derived xenografts with or without DM and in those with CEBPD‐overexpressing cell‐derived xenografts without DM." (PMID 34954904, 2021). "Combined with the observations that CEBPD triggers growth arrest, participates in the bortezomib-induced cell death and activates miR-744, miR-3154 and miR-3162, we further provided a novel mechanism that miRNAs serve as tumor suppressors by eliciting DNA methylation on gDNA in leukemic cells." (PMID 29120412, 2017). "In addition, CEBPD has been suggested to serve as a potent tumor suppressor." (PMID 28099155, 2017). "Moreover, the results of this study also implied that the dissection of CEBPD’s roles in the tumor microenvironment could provide a great opportunity to develop a feasible translational application for cancer therapy." (PMID 25591788, 2015). "The study agreed with the speculation that CEBPD acts as a tumor suppressor in cancer cells." (PMID 25591788, 2015). "We nominate CEBPD and TNFRSF1A/ITGB1 as actionable nodes and identify ARRDC3 as a spatially restricted effector with context-dependent tumor-modulatory functions warranting therapeutic exploration." (PMID 41235227, 2025). "We obtained approximately 0.3–0.5% B220+CD11c+NK1.1+ NK cells in tumor-bearing mouse liver CD45+ cells, which were then treated with control siRNA or CEBPδ-siRNA." (PMID 36890150, 2023). "Presumably due to its capacity to interfere with the activity of CEBPB (and perhaps additional binding partners such as CEBPD), ST101 compromises the growth and survival of brain and other tumor cells in vitro and in vivo." (PMID 36831248, 2023). "It is clear from the literature reviewed above that a major response of brain and other tumor cells to ATF5, CEBPB and CEBPD knockdown or interference with activity is the appearance of apoptotic cell death." (PMID 36831248, 2023). "The results showed that knocking down the expression of CEBPD and FOSL1 significantly reduced cells' invasive ability under hypoxic conditions, implying an important role of CEBPD and FOSL1 in hypoxia-induced tumor invasion." (PMID 37441593, 2023). "Our results suggested that FOSL1, CEBPD, MXI1 and YY1 were critical TFs of tumor invasion induced by hypoxia, and they can be used as an independent prognostic signature to predict GBM survival." (PMID 37441593, 2023).